CD200 (CD200 molecule)
Diseases named in the same sentence as CD200 in open-access papers (continued):
Sharing a sentence is not in itself a finding about the gene and the disease.
acute myeloid leukemia (21 papers, 2015 to 2025). Acute myeloid leukemia (AML) is a group of neoplasms arising from precursor cells committed to the myeloid cell-line differentiation. "Clinically, the expression of CD200 was associated with poor prognosis in multiple myeloma and acute myeloid leukemia." (PMID 41233805, 2025). "Additionally, for acute myeloid leukemia, CD200 expression was significantly associated with worse survival." (PMID 26910908, 2016). "In this study, CD200 was found to be selectively enriched in CD45dim blasts as compared to the more differentiated CD45high cells in acute myeloid leukemia (AML)." (PMID 41233805, 2025). "We studied the expression of CD200 in a series of 244 patients with diagnosis of acute myeloid leukemia (AML), to evaluate its impact on outcome and its possible association with other known prognostic factors." (PMID 26338961, 2015). "In acute myeloid leukemia, CD200 expression led to impaired NK cell killing." (PMID 36074574, 2022). "Moreover, the findings in the current study demonstrated that CD200 positive expression was an independent predictor of MDS transformation to acute myeloid leukemia." (PMID 32856848, 2020). "The clinical utility of samalizumab, an anti-CD200 monoclonal antibody, is currently in being investigated in an open label phase Ib/II clinical trial to evaluate its therapeutic efficacy in newly diagnosed acute myeloid leukemia (NCT03013998)." (PMID 32703985, 2020). "One study found that introduction of a human anti-CD200 monoclonal antibody was able to successfully enhance immune responses against acute myeloid leukemia (AML)." (PMID 36756156, 2023). "For example, the increased expression of CD200 and galectin-9 on cancer cells (ligands of CD200R and TIM-3 on NK cells, respectively) has been demonstrated in acute myeloid leukemia (AML)." (PMID 38254135, 2024). "After 36-month follow-up; the subgroup of MDS patients with high expression of CD200; and high serum CTLA-4 concentrations showed high death rate and high frequency of acute myeloid leukemia transformation." (PMID 32856848, 2020). "CD200 is an immunosuppressive molecule overexpressed in several hematological malignancies including B-CLL, MM, and acute myeloid leukemia (AML)." (PMID 26425544, 2015). "We herein, study the expression level of CD200 and CD56 in de-novo acute myeloid leukemia patients to estimate the prognostic value of their positive expressions individually in AML cases." (PMID 32212802, 2020). "CD200 and BCL2 overexpression is independently associated with inferior survival in acute myeloid leukemia (AML), and these two factors are frequently co-expressed; however, no data are available on the role of concomitant aberrant CD200 and BCL2 expression on outcome of AML patients." (PMID 33596632, 2021).
leukemia (19 papers, 2013 to 2026). A malignant (clonal) hematologic disorder, involving hematopoietic stem cells and characterized by the presence of primitive or atypical myeloid or lymphoid cells in the bone marrow and the blood. "Mice with leukemia injected with CD200+ FBL (B6 Friend virus-induced erythroleukemia) cells exhibited improved survival when treated with T cells transduced with the CD200R–CD28 fusion protein." (PMID 37894750, 2023). "Targeting CD200 on leukemia blasts presents an insightful strategy to reduce relapse rates and improve outcomes in AML patients." (PMID 34220833, 2021). "We aimed to elucidate the prognostic role of CD200/BCL2 co-expression and its association with specific leukemia subsets." (PMID 33596632, 2021). "The authors postulate that deletions of the following genes ETV6, VPREB1, CDKN2A/B, TBL1XR1, PAX5 as well as BTLA and CD200 are very early and essential events in leukemia development." (PMID 27933341, 2016). "So, the combination of CD200 expression and leukemia type define three group of patients with significant different survival expectation (p = 0,0007)." (PMID 26338961, 2015). "Paired receptors are an increasingly important group of targets as indicated by CD200/CD200R in leukemia and CD47/SIRP in many cancers." (PMID 23691022, 2013). "Moreover, the high expression of CD200 on leukemia cells, through binding to CD200R, inhibits the cytotoxicity of NK cells, inducing immune evasion of leukemia cells, which is associated with the recurrence and progression of AML." (PMID 40008144, 2025). "As expected, genes associated with AML proliferation (FLT3, KIT), leukemia stem cells (CD34, CD38, and IL1RAP), and candidate genes overexpressed in AML (CD99, CD200, and LAMP2) were downregulated after chemotherapy, consistent with recent scRNA-Seq and immunohistochemistry data." (PMID 36099049, 2022). "CD200 was more frequent in secondary compared to de novo leukemia (p = 0.0006), in CD34 positive cases (p = 0.00001), in Bcl2 overexpressing cases (p = 0.01), in those wild-type Flt3 (p = 0.004) and with favorable or unfavorable compared to intermediate karyotype (p = 0.0003)." (PMID 26338961, 2015). "When K562 human leukemia cells expressing high levels of CD200 (high-CD200) were exposed to regular NK cells in vitro, CD107a levels decreased in comparison to K562 cells expressing low levels of CD200 (low-CD200), confirming that the suppression of NK cell activity was CD200-related." (PMID 36756156, 2023). "Moreover CD200 was more frequently expressed secondary than in de novo leukemia (73% vs 49%)." (PMID 26338961, 2015). "CD200Fc, which links the extracellular domain of CD200 with the murine IgG2a Fc region, effectively inhibits resistance to tumor growth in CD80-transfected EL4 or C1498 leukemia tumor cell allograft mice." (PMID 37894750, 2023). "In addition, Kasumi-1 exosomes also carried proteins known to be expressed in leukemia stem cells: CD44, CD200 and CD105." (PMID 25093329, 2014). "The CD200/CD200R interaction has similarities with the CD47 interaction with the SIRP paired receptor family in that both ligands are widely distributed but receptors are restricted mainly to myeloid cells and both CD200 and CD47 are targets for leukemia therapy." (PMID 23602662, 2013). "The negative impact of CD200 on remission probability was maintained in multivariate analysis (p = 0.04), along with more conventional factors such as age (p = 0.002), type of leukemia (p = 0.002), CD34 positivity (p = 0.008) and unfavorable cytogenetic risk (p = 0.0025)." (PMID 26338961, 2015).
autoimmune disease (18 papers, 2012 to 2024). A disorder resulting from loss of function or tissue destruction of an organ or multiple organs, arising from humoral or cellular immune responses of the individual to their own tissue constituents. "This double staining has never been associated with MS, but a reduction in the number of CD19/CD200 B lymphocytes has recently been described in the acute phase of severe alopecia areata, a hair follicle-specific Th1 cell-mediated autoimmune disease." (PMID 30498433, 2018). "CD200 deficient (CD200–/–) mice display increased susceptibility to T cell-mediated autoimmune diseases and have greater sensitivity to influenza infection, largely due to a failure in regulation of airway macrophages." (PMID 22496920, 2012). "Furthermore, a low level of CD200 has been implicated in autoimmune diseases, while recombinant CD200 has shown potential for alleviating airway hyperresponsiveness in a murine model." (PMID 38780647, 2024). "Likewise, CD200 expression regulates levels of inflammation associated with various autoimmune diseases." (PMID 36756156, 2023). "In conclusion, we speculate that CD200/CD200R1 might play a general immunosuppressive role and that CD200-Fc may be of value for the treatment of autoimmune disorders caused by dysfunction of DCs in NZB/WF1 mice." (PMID 27545083, 2016). "A decrease in CD200 expression has been shown in other neurological disorders such as spinal cord injury, but also in neurodegenerative disorders, aging and autoimmune diseases." (PMID 35681481, 2022). "CD200:CD200R1 interaction has been shown to suppress immune responses in autoimmune disorders, infectious diseases, transplantation, and cancer." (PMID 28234914, 2017). "In rodents, blocking CD200/CD200R1 binding was found to aggravate the clinical course of experimental autoimmune diseases." (PMID 26690123, 2015). "The beneficial effects of CD200 were demonstrated in prior animal studies which found that the CD200/CD200R pathway lowered levels of inflammation and disease susceptibility in different autoimmune disease models, including those of arthritis and multiple sclerosis." (PMID 36756156, 2023). "IL-6, IL-8, and CD200 play an important role in arthritis and other autoimmune diseases." (PMID 36011369, 2022). "Similar findings in the context of several autoimmune diseases imply that the dysregulation of the CD200/CD200R axis may be involved in their pathogeneses." (PMID 32967175, 2020). "These mice had an increased susceptibility to autoimmune diseases, including EAE and CIA, consistent with the hypothesis of a general immunoregulatory role for CD200." (PMID 28234914, 2017). "Consistent with this premise, dysfunction in CD200/CD200R1 signaling has been reported in numerous autoimmune diseases, including Parkinson’s disease, Alzheimer’s disease, rheumatoid arthritis, uveoretinitis, lupus, autoimmune and inflammatory skin disorders and spontaneous fetal loss." (PMID 26690123, 2015). "CD200/CD200R1 signaling has been suggested to play a role in the induction of autoimmune diseases." (PMID 26690123, 2015). "While available evidence highlighted an important role of CD200/CD200R1 in experimental autoimmune diseases, the role of CD200/CD200R1 in human autoimmune diseases such as SLE remains unknown." (PMID 22621248, 2012). "The impact of the CD200/CD200R-signaling pathway on several inflammatory and autoimmune diseases has been described." (PMID 32967175, 2020). "As such, it is possible that loss of Adamts12 with subsequent loss of CD200/CD200R fibroblast-macrophage signaling leads to a dysfunctional attenuation of inflammation in response to other stimuli, i.e., in infection and autoimmune disease, but not fibrosis." (PMID 39286973, 2024). "Experimental studies have revealed that CD200/CD200R1 signaling pathway has an immunosuppressive effect on the inflammatory cellular immune response and maintains immune homeostasis in the context of autoimmune diseases." (PMID 34101054, 2021).
autoimmune disease (continued). "Mice lacking CD200 display elevated numbers of activated macrophages and develop more aggressive autoimmune diseases 2, 3, suggesting that CD200 restrains the tonic activation of macrophages to promote homeostasis." (PMID 31365119, 2019). "Lack of this regulatory pathway in Cd200–/–mice leads to exacerbation of autoimmune diseases e.g. autoimmune encephalomyelitis and collagen-induced arthritis in mice." (PMID 30653571, 2019).
Stroke (17 papers, 2018 to 2025). Sudden impairment of blood flow to a part of the brain due to occlusion or rupture of an artery to the brain. "Here, we propose that the CD200/CD200R signaling pathway contributes to spontaneous functional recovery after stroke by restraining synapse loss through inhibiting microglia activation and pro-inflammatory factor release." (PMID 32473633, 2020). "Using CD200-deficient mice, or overexpression of CD200, using conditional systems in various experimental stroke models with long-term recovery would be interesting to further elucidate its function in neuroinflammation and potential as a therapeutic target." (PMID 30319362, 2018). "Exercise improves the inflammatory environment after stroke by activating the CD200/CD200R signaling pathway, which has a beneficial effect in promoting neurogenesis and functional recovery." (PMID 39691417, 2024). "CD200R1 is the receptor for CD200 and has been involved in the inhibition of neuroinflammatory pathways in aging, stroke, and multiple sclerosis." (PMID 36012423, 2022). "Microglia can also regulate post-stroke plasticity through other mediators such as microglia-neuron interactions mediated by the neural factors CD200 and CX3CL1." (PMID 34831273, 2021). "The role of CD200-DC200R interaction in post-stroke functional recovery has been recently supported by Sun and colleagues, who confirmed that CD200/CD200R signaling pathway contributes to spontaneous functional recovery in rats subjected to MCAO." (PMID 34831273, 2021). "CD200 was highly expressed in the early stage and then decreased 7 days after stroke onset, whereas the expression of CD200R1 increased over time." (PMID 33067924, 2020). "In this study, we did not distinguish between microglia and infiltrating myeloid cells, and CD200R deficient on microglia transgenic mice would be helpful to explore the role of CD200/CD200R signaling on microglia after stroke in the future studies." (PMID 32473633, 2020). "In this study, we used a transient middle cerebral artery occlusion (MCAO) model in rats to investigate the function of CD200/CD200R signaling in spontaneous functional recovery after stroke." (PMID 32473633, 2020). "This suggests that activating the CD200/CD200R signaling pathway downregulates p-MAPK expression after stroke in rats." (PMID 32473633, 2020). "Temporal and regional changes in CD200 gene and protein expression have also been described in rodents after stroke." (PMID 30777093, 2019). "The long-term impact of stroke on CD200 expression and its contribution to chronic neurodegeneration remains to be seen." (PMID 30777093, 2019). "Our study has identified activated peripheral immune cells as the predominant CD200R1 expressers in stroke, providing new cellular targets for systemically administered CD200 supplementation therapies." (PMID 30777093, 2019). "Additionally, in animal stroke models, CD200 fusion protein (CD200Fc) enhances synaptic plasticity by inhibiting microglial activation and inflammatory factor release, thereby promoting spontaneous functional recovery." (PMID 41221273, 2025). "As a novel anti-inflammatory target, CD200 plays an important role in maintaining immune homeostasis by regulating macrophages in a wide range of inflammatory diseases, such as atherosclerosis, stroke, influenza and colitis." (PMID 41221273, 2025). "Thus, the CD200/CD200R signaling pathway plays an important role in neurological recovery by regulating synaptic plasticity in stroke, which is worthy of further study." (PMID 38727249, 2024). "For instance, interacting OX-2 membrane glycoprotein (CD200) and Cell surface glycoprotein CD200 receptor 1, both associated to acute stroke severity and neurological outcome in the present study are involved in post-stroke inflammation." (PMID 36418382, 2022).
Stroke (continued). "CD200 is involved in the immunoregulatory mechanism and may provide a promising treatment strategy in neuroinflammatory diseases, like stroke, cerebral ischemia, Alzheimer’s disease, Parkinson’s disease, multiple sclerosis." (PMID 33860454, 2021). "Authors showed that post-stroke intracerebroventricular injection of CD200 (as an agonist of CD200R) improved sensorimotor function in a battery of behavioral tests: Longa test, adhesive removal test, limb-use asymmetry test and the modified grip-traction test." (PMID 34831273, 2021). "However, a comprehensive characterization of CD200/CD200R1 regulating the inflammatory response signals in stroke injury is still few." (PMID 33067924, 2020). "However, there are few data available on how the CD200/CD200R1 signaling pathway regulates neuronal inflammation after stroke." (PMID 33067924, 2020). "Activation of the CD200/CD200R signaling pathway further promoted functional recovery after stroke." (PMID 32473633, 2020). "Activating CD200/CD200R signaling may be insufficient to contain the NF-κB pathway after stroke in vivo." (PMID 32473633, 2020). "However, the effect and mechanism of action of the CD200/CD200R pathway in spontaneous functional recovery after stroke are unclear." (PMID 32473633, 2020). "The CD200/CD200R signaling pathway participates in spontaneous functional recovery after stroke." (PMID 32473633, 2020). "CD200 mRNA levels were lower in the ischemic core during the first week after stroke." (PMID 30777093, 2019). "Interestingly, another study found that after SCI, proliferating endothelial cells located in the core of the lesion upregulate CD200, which hinders inflammation, while yet another study found that treadmill exercise upregulates both CD200 and its receptor after stroke in rats." (PMID 34064332, 2021). "Therefore, the CD200/CD200R signaling pathway could be a potential therapeutic target for functional recovery after stroke." (PMID 32473633, 2020). "Exercise significantly increases CD200 and CD200R levels in the ipsilateral hippocampus and cortex after stroke." (PMID 39691417, 2024). "Treadmill exercise plays a beneficial role in promoting neurogenesis and functional recovery by activating the CD200/CD200R signaling pathway and improving the inflammatory environment after stroke." (PMID 35310096, 2022). "First, CD200 was expressed in ischemic neurons, and the expression of CD200R1 was in lymphocytes located in the ischemic brain after stroke." (PMID 33067924, 2020). "In this study, the expression of CD200 and CD200R1 was altered at early phases in the ischemic penumbra of stroke mouse brains." (PMID 33067924, 2020). "In this study, we observed the expression of CD200 and CD200R1 on infiltrating lymphocytes in the brain after stroke and the diversity of the neuroinflammatory response in acute stroke." (PMID 33067924, 2020). "Consequently, CD200 could play an important role in therapeutic strategies for the treatment of ischemic stroke by way of the inhibition of detrimental leukocyte activation and improvement of stroke-induced lymphopenia." (PMID 33317034, 2020). "In this study, the results showed that the dynamics of CD200 and CD200R1 expression present mismatches 7 days after stroke." (PMID 33067924, 2020). "In the same model, CD200 and CD200R levels in the ipsilateral hippocampus and cortex were elevated after treadmill exercise, which improved the inflammatory environment and promoted neurogenesis and functional recovery after stroke." (PMID 38727249, 2024). "Recent studies indicated that the CD200/CD200R signaling pathway regulates the microglia activation-induced inflammatory response and synaptic plasticity in vitro and in vivo, but few studies have been performed in stroke." (PMID 32473633, 2020). "ELISA measurement of CD200 protein concentrations in the ischemic brain (a) and plasma (b) 72 h after stroke shows no significant change in wild-type mice (N = 5–8/group)." (PMID 30777093, 2019).
Stroke (continued). "To investigate whether the CD200/CD200R signaling pathway is involved in regulating microglia activation and inflammatory factor release after stroke in rats, we assessed microglia activation using immunofluorescence and inflammatory factor (such as Il-1β, Il-6, Tnf-α, Il-4, and Cd206) release." (PMID 32473633, 2020). "No change in CD200 concentration was found in the brain or plasma after stroke in WT mice." (PMID 30777093, 2019).